ANK2 (ankyrin 2)
Diseases named in the same sentence as ANK2 in open-access papers (continued):
Sharing a sentence is not in itself a finding about the gene and the disease.
developmental delay (2 papers, 2023 to 2024). "In addition, ANK2 is located on the 4q deletion, previously linked to congenital anomalies affecting different body systems, including developmental delay, cardiac involvement and polycystic kidney or isolated kidney." (PMID 39350038, 2024).
gastric cancer (2 papers, 2020). A primary or metastatic malignant neoplasm involving the stomach. "In addition, ectopic expression of miR-126, miR-647 and miR-1284, which are evidently downregulated in drug-resistant SGC7901/VCR gastric cancer cells, could sensitize gastric cancer cells to VCR by inhibiting expression of EZH2, ANK2 and EIF4A1, respectively." (PMID 32192494, 2020).
hypertrophic cardiomyopathy (2 papers, 2022 to 2024). A condition in which the myocardium is hypertrophied without an obvious cause. "Further population and laboratory studies are required to fully elucidate the connection between ANK2 variants and hypertrophic cardiomyopathy, which could involve ANKB interactions with structural/cytoskeletal elements within cardiac cells." (PMID 35990955, 2022). "CRYAB modulates cardiomyocyte apoptosis in cardiac disorders, ANK2 regulates cardiac ion channels, and MYOZ2 mutations are linked to hypertrophic cardiomyopathy." (PMID 38559672, 2024).
myocardial ischemia (2 papers, 2019 to 2023). A disorder of cardiac function caused by insufficient blood flow to the muscle tissue of the heart. "Despite the fact, our findings may have implications for the diagnosis/prognosis and treatment of CAVS and the mitochondrial function-related proteins such as LRRK2 and ANK2 screened by CAVS bio-signal are important for the regulation of mitochondrial function in CAVS-induced myocardial ischemia." (PMID 30651404, 2019). "Our results also showed a decrease in ANK2 expression in CAVS, suggesting that the mitochondria and vesicle transport may be disrupted in myocardial ischemia induced by CAVS." (PMID 30651404, 2019).
thyroid cancer (2 papers, 2020 to 2022). "First, we verified the expression of 9 immune-related prognostic factors, AKAP12, APOC1, TIMP3, ADAMTS9, ANK2, HTRA3, SYNDIG1, ​​ADAMTS5 and DACT1, in 11 thyroid cancer cell lines in the CCLE database." (PMID 36591507, 2022).
type 2 diabetes (2 papers, 2007 to 2022). "In particular, the ANK2 p.R1788W variant, which is associated to cardiac phenotypes, was enriched in individuals of white and Hispanic descent diagnosed with type 2 diabetes in the American Diabetes Association GENNID cohort." (PMID 35990955, 2022). "Moreover, the ANK2 p.L1622I variant, associated with a less severe cardiac phenotype, is the most frequent ANK2 variant (7.5%) in African Americans who carry up to a 2-fold increased risk for type 2 diabetes." (PMID 35990955, 2022). "The high levels of ankyrin-B expression in the brain and pancreatic beta cells and early senescence in ankyrin-B+/− mice suggests that human populations with age-related neurological disorders and/or type 2 diabetes should be evaluated for ANK2 variants." (PMID 17940615, 2007). "With type 2 diabetes also linked to specific ANK2 antecedents, the putative compounding effects of metabolic perturbation on cardiac and neurological phenotypes may pose additional risk to individuals carrying ANK2 variants." (PMID 35990955, 2022).
aneurysm (1 paper, 2019). Bulging or ballooning in an area of an artery secondary to arterial wall weakening. "We selected and validated the genes randomly (Lrrc17, Gxylt2, Mfsd2a, Scube and Ank2) and based on their role in aneurysms (Mmp12, Spp1, Ctss) or cardiovascular complications (Mfap4, Igfbp2) or inflammatory signalling pathways (Ccls and Ccrs)." (PMID 30677223, 2019).
attention deficit-hyperactivity disorder (1 paper, 2026). A disorder characterized by a marked pattern of inattention and/or hyperactivity-impulsivity that is inconsistent with developmental level and clearly interferes with functioning in at least two settings (e.g. at home and at school). "An analysis of rare genetic variants identifies three genes—MAP1A, ANO8 and ANK2—that have a role in attention deficit hyperactivity disorder (ADHD) and investigates the potential underlying biological mechanisms." (PMID 41224997, 2026).
cardiac hypertrophy (1 paper, 2020). "Additionally, a long non-coding RNA related to cardiac hypertrophy, Chaer1, and genes related to hereditary arrhythmic disorders, including Ank2, Gpd1l, and Cacna2d1, were downregulated in the Rbm20S637A/S637A mice." (PMID 33110103, 2020).
cervical cancer (1 paper, 2022). A primary or metastatic malignant neoplasm involving the cervix. "These target genes were crossed with mRNAs that are downregulated by more than fivefold in cervical cancer from The Cancer Genome Atlas (TCGA) database, and 8 target genes were finally obtained (OGN, SCN7A, PGR, PTGER3, FGF7, ADAMTS5, LMO3 and ANK2)." (PMID 35513835, 2022).
deafness (1 paper, 2020). An inherited or acquired condition characterized by the complete loss of the ability to hear from one or both ears. "Interestingly, the significant deafness phenotype might be intensified by the variant in ANK2, also expressed in the cochlea and fundamental for the mechanosensitive response for hearing." (PMID 33374679, 2020).
focal epilepsy (1 paper, 2025). A seizure caused by a localized disorder. "The prevalence of ANK2 pathogenic variants in apparent self‐limited focal epilepsies may be underrated and worth further investigation." (PMID 39962910, 2025). "Our family, however, demonstrated that ANK2 pathogenic variants can be associated with familial focal epilepsies without CV phenotypes." (PMID 39962910, 2025).
glaucoma (1 paper, 2025). Increased pressure in the eyeball due to obstruction of the outflow of aqueous humor. "Interestingly, while no studies have yet directly linked ANK2 with glaucoma, our previous study identified miRNA 3167 and miRNA 876-5P targets as significantly enriched in glaucoma patients, with ANK2 emerging as a shared target." (PMID 41042282, 2025).
Hypertension (1 paper, 2023). The presence of chronic increased pressure in the systemic arterial system. "A pressure overload model has not previously been shown to predispose to ACM, and to our knowledge, there is no clinical data to suggest that pressure overload or hypertension exacerbates clinical phenotype in the setting of an ANK2 variant." (PMID 37182735, 2023).
Insulin resistance (1 paper, 2022). Increased resistance towards insulin, that is, diminished effectiveness of insulin in reducing blood glucose levels. "The increase in adiposity is also observed in adipose tissue-specific Ank2 knockout mice, which develop progressive pancreatic islet dysfunction, accumulation of fat with age or high fat diet, and insulin resistance associated with impaired glucose co-transporter clathrin-mediated endocytosis." (PMID 35990955, 2022). "Notably, older ANK2 R1788W mice had increased adiposity and showed insulin resistance." (PMID 35990955, 2022). "A knock in ANK2 p.L1622I model exhibited a measurable and distinct cardiac phenotype, reduced ANKB expression, and even developed insulin resistance and age-dependent increases in adiposity." (PMID 35990955, 2022).
lung adenocarcinoma (1 paper, 2022). A carcinoma that arises from the lung and is characterized by the presence of malignant glandular epithelial cells. "ANK2 expression was significantly lower in lung adenocarcinoma cell lines (PC9, H1975, A549 and HCC827, all P < 0.05) than in healthy lung epithelial cell line (BEAS-2B)." (PMID 36539782, 2022).
lung carcinoma (1 paper, 2022). "The CPTAC database revealed that ANK2 expression was lower compared to healthy tissues across multiple cancers, including lung cancer." (PMID 36539782, 2022). "In terms of lung cancer, ANK2 has not been studied and we proved that ANK2 was downregulated in LUAD." (PMID 36539782, 2022).
muscular dystrophies (1 paper, 2020). "Of note, the proteins encoded by genes linked to other muscular dystrophies such as COL6A1, CAV3, DYSF, DMD, TTN, and VCP and the strongest family sequencing candidates INTS1 and ANK2 were all found in nuclear envelope proteomics datasets." (PMID 31862442, 2020).
nasopharyngeal carcinoma (1 paper, 2020). A carcinoma arising from the nasopharyngeal epithelium. "One previous study compiled datasets for nasopharyngeal cancer and found ANK2 to be hypomethylated and upregulated, highlighting it as a potential biomarker for this cancer type." (PMID 33218035, 2020).
osteoarthritis (1 paper, 2018). A noninflammatory degenerative joint disease occurring chiefly in older persons, characterized by degeneration of the articular cartilage, hypertrophy of bone at the margins and changes in the synovial membrane. "Likewise upregulation of ANK2, in both the groups was predicted to inhibit MYBBP1, which was leading to development of osteoarthritis by NF-κB activation through activation of IL-1β similar to activation of TLR2 by upregulated fibronectin." (PMID 29731966, 2018).
pterygium (1 paper, 2025). A wedge-shaped fibrovascular lesion arising from the bulbar conjunctiva and extending to the cornea. "ANK2 downregulation has been reported in pterygium, another eye condition characterized by abnormal tissue growth." (PMID 41042282, 2025).
rectum adenocarcinoma (1 paper, 2020). An adenocarcinoma arising from the rectum. "The result illustrated that the hub genes, including NRXN1, ANK2, LPHN2, APOE, TLR8, ESR1, and so on, might be critical for rectum adenocarcinoma, and m6A modification could regulate the abnormal expression of these genes." (PMID 33680913, 2020).
Timothy syndrome (1 paper, 2024). "Moreover, there are three atypical LQTS or multisystem syndromic disorders including Ankyrin-B syndrome gene ANK2 (LQT4), Anderson–Tawil syndrome (ATS) gene KCNJ2 (LQT7), and Timothy syndrome (TS) gene CACNA1C (LQT8)." (PMID 38666937, 2024).
cancer (18 papers, 2016 to 2025). A tumor composed of atypical neoplastic, often pleomorphic cells that invade other tissues. "Using the cBioportal database, we first evaluated the ANK2 mutation frequency across multiple cancers." (PMID 36539782, 2022). "The Cancer Genome Atlas (TCGA) PanCancer Atlas studies in cBioportal were used to evaluate the mutation frequency of ANK2 across multiple cancers." (PMID 36539782, 2022). "ANK2 has a high mutation frequency in some cancers and silencing of ANK2 expression reduces the growth and invasion of cancer cell type." (PMID 36591507, 2022). "The loss of ANK2 could reflect the physiological changes that occur in the gut during cancer development, including the loss of muscle function in the tumour." (PMID 35842572, 2022). "Moreover, the role of cancer associated aberrant methylation in ANK2 remains largely unknown." (PMID 33218035, 2020). "The expression status and role of ANK2 seems to vary amongst cancer types, and further investigation in a larger variety of cancers is required to better understand its relationship to cancer." (PMID 33218035, 2020). "These four pathways were proteoglycans in cancer (ANK2, FASLG, HSPG2, PTPN11, STAT3, and VEGFA), HIF-1 signaling (ARNT, STAT3, and VEGFA), FoxO signaling (FASLG, SMAD4, and STAT3), and ECM-receptor interaction (HSPG2 and LAMA2)." (PMID 29300322, 2018). "Therefore, ANK2 mutation might enhance the immunogenicity of LUAD, hence boosting the cancer-immunity cycle." (PMID 36539782, 2022). "For DSS, biomarker candidates for unfavorable prognosis for EC (CNN1) and the key cell development protein ANK2 (MC) have presented oncogenic properties in EOC and other cancers, respectively." (PMID 40778374, 2025). "ANK2-MT LUAD was characterized by high expression of chemokines (CXCL9, CXCL10, CXCL11, and CXCR3) involved in the recruitment of anti-cancer immune cells." (PMID 36539782, 2022). "CD4+CD45RO+ T cells in the lesional blood highly expressed genes relating to cancer progression and CTCL pathogenesis: RGS1, RDH10, HES1, DNAH9, ANK2, and SGK1 16–25." (PMID 34608214, 2021). "These identified CMT DMRs were found in CpG islands in the 21st and 1st introns of ANK2 and EPAS1, respectively, and the increase in methylation in the cancer samples are shown via linear mixed model (LMM) with thresholds of both 10% and 5%." (PMID 33218035, 2020). "Additional variants, including MUC5B, DNAH11, ANK2, and LAMA5, which were not part of tier-1 genes but has been reported in other gastrointestinal patients (according to the Cancer Browser) were also consistently detected." (PMID 37878600, 2023). "Notably, at least two of the FOXA2 transcriptional targets identified by our analysis (ANK2 and RAB3C) are known to promote cancer progression and metastasis." (PMID 33793068, 2021).
infection (11 papers, 2007 to 2024). The state of being infected such as from the introduction of a foreign agent such as serum, vaccine, antigenic substance or organism. "Infection with Wolbachia was detected in all specimens examined and specific ank2 and pk1 PCR-products were observed." (PMID 26818097, 2016). "Specific ank2 and pk1 PCR assays indicated the occurrence of infection by Wolbachia in all the examined specimens, showing that infection is fixed in all Cx. quinquefasciatus, Cx. p. pipiens form pipiens, Cx. p. pipiens form molestus and Cx. p. pallens populations examined here." (PMID 24006922, 2013).
tumor (10 papers, 2016 to 2026). "Taken together, these results suggested that high ANK2 expression was associated with immunologically “hot” tumor microenvironment and enhanced anti-tumor immunity." (PMID 36539782, 2022). "Co‐expression network analysis revealed that ANK2 was a hub gene associated with some validated tumor suppressors." (PMID 30381870, 2019). "Moreover, we analyzed the impact of ANK2 mutation or expression on immune-related signatures in tumor immune microenvironment (TIME) using TISIDB." (PMID 36539782, 2022). "Importantly, ANK2 mutation or high ANK2 expression was associated with the development of enhanced anti-tumor immunity." (PMID 36539782, 2022). "Furthermore, the impact of ANK2 mutation and expression on the tumor immune microenvironment of LUAD was analyzed using TCGA and TISIDB databases." (PMID 36539782, 2022). "Moreover, ANK2 (ANK2 mutation or high ANK2 expression) is related to strengthened tumor immunogenicity and inflamed antitumor immunity, which could be the underlying mechanism for the function of ANK2 in LUAD." (PMID 36539782, 2022). "The tumor suppressor role of the selected genes ANK2 and NLGN3 was elucidated by cell viability assay, transwell migration, colony-forming and wound healing assay in MCF7, MDA-MB-231 and MCF10A cell lines." (PMID 38977697, 2024). "Data from TIMER2.0 database reveals that the mutation frequency of ANK2 reached 19% in LUAD and SKCM, while in UCEC, LUSC, and COAD, the mutation rate exceeded 10% of the tumour samples." (PMID 39317949, 2024). "When ANK2 is expressed, there is a noticeable inhibition of tumour cell proliferation, migration and invasion." (PMID 39317949, 2024). "We could experimentally show that the NLGN3 & ANK2 have tumor-suppressor roles in BRCA as shown by cell viability assay, transwell migration, colony forming and wound healing assay." (PMID 38977697, 2024). "Furthermore, different highly O-glycosylated protein coding genes, such as mmp9, ecm1 and ank2, were upregulated in 4T1/Tn+ tumor cells." (PMID 38245559, 2024). "Furthermore, this study reports that different highly O-glycosylated protein-coding genes, such as mmp9, ecm1, and ankyrin-2 were upregulated in 4T1/Tn+ tumor cells." (PMID 38245559, 2024). "Furthermore, different highly O-glycosylated protein-coding genes, such as mmp9, ecm1 and ankyrin-2, were upregulated in 4T1/Tn+ tumor cells." (PMID 38245559, 2024). "Firstly, ANK2 expression was compared between tumor tissues and healthy tissues." (PMID 36539782, 2022). "Moreover, TUNEL and angiogenesis assays showed that overexpression of ANK2 significantly promoted cell apoptosis and inhibited angiogenesis, suggesting that ANK2 may function as a key tumor suppressor in CRC." (PMID 41626625, 2026). "In addition, tumor immunogenicity between ANK2-MT and ANK2-WT LUAD were compared." (PMID 36539782, 2022). "Consequently, ANK2-MT LUAD exhibited a TIME characterized by increased anti-tumor immune cells." (PMID 36539782, 2022). "In our study, high PNB were observed in the ANK2-MT LUAD, indicating that the ANK2-MT LUAD had heightened tumor immunogenicity." (PMID 36539782, 2022). "Moreover, ANK2 mutation or higher ANK2 expression correlated with enhanced antitumor immunity and “hot” tumor microenvironment in LUAD, which could be potential mechanisms that ANK2 mutation facilitated ICIs therapy and patients with higher ANK2 expression survived longer." (PMID 36539782, 2022). "ANK2 and DCAF17 were extracted in tumor tissue of patients with different prognosis." (PMID 27564264, 2017).
neurological disorders (7 papers, 2015 to 2025). "Ankyrin-2 deficiency has been associated with blood, cardiac and neurological disorders due to its implication in the correct functioning of calcium channels and transporters." (PMID 31899766, 2020). "Separately, ANK2 is also emerging as a gene of interest in neurological disorders." (PMID 35990955, 2022). "Besides the significance of ANK2 in ASD, neuronal pathways involving the AnkB440-L1CAM complex are also relevant to other neurological diseases." (PMID 34812142, 2021).
heart disease (5 papers, 2019 to 2025). "The proband’s family has an elevated heart disease risk, particularly the son (II-2) with the ANK2 variant." (PMID 41287789, 2025). "Notably, intense endurance exercise or other genetic variants likely play a role in the development of cardiac disease associated with loss-of-function ANK2 variants." (PMID 33868385, 2021). "By emphasizing the need for further research, this review aims to enhance understanding of ANK2’s role in heart disease and guide the development of effective therapies." (PMID 39867173, 2025). "While cardiomyocyteshave been the focus of ANK2 research, the potential role ofANK2 in other myocardial cells in heart diseases is an area thatrequires further investigation." (PMID 39867173, 2025).
cardiovascular disease (4 papers, 2017 to 2025). "Further investigation is warranted to elucidate the rolesof these ANK2 variants in cardiovascular diseases, particularlyregarding their influence on the development and progression of structural heartdiseases." (PMID 39867173, 2025). "Despite progress in identifying ANK2 variants and their potentialimplications in cardiovascular diseases, significant gaps in our understandingpersist." (PMID 39867173, 2025). "As in the case of many cardiovascular disease genes, the penetrance of phenotypes in ANK2 variant carriers is variable." (PMID 29163198, 2017). "Alterations in Ankyrin-B and Ankyrin-G have been linked to neuropsychiatric and cardiovascular disorders in humans, suggesting that Ank2 regulation by sertraline could impact neuronal plasticity and stability." (PMID 39859278, 2025). "This review explores the relationshipbetween ANK2 gene variants and their associated cardiac phenotypes, summarizes recent findings on genetic mechanisms and clinical impacts,and highlights areas for future research to enhance understanding and improvetherapies for cardiovascular diseases." (PMID 39867173, 2025). "Among cardiovascular disease-relevant, differentially methylated genes in males, Atg5, Ank2, Cux1 and Lamp2 exhibited significant increases in gene expression." (PMID 33445541, 2021).